IFIH1 (interferon induced with helicase C domain 1)
Diseases named in the same sentence as IFIH1 in open-access papers (continued):
Sharing a sentence is not in itself a finding about the gene and the disease.
AIDS (3 papers, 2023 to 2024). A syndrome resulting from the acquired deficiency of cellular immunity caused by the human immunodeficiency virus (HIV). "In conclusion, this meta-analysis showed that the IFIH1 rs1990760 polymorphism A allele and IFIH1 rs3747517 polymorphism C allele were associated with AIDs." (PMID 37426657, 2023). "Researchers also identified an association between several SNPs in the IFIH1 gene with the risk of various AIDs, such as SLE, GD, and psoriatic arthritis (PsA)." (PMID 37426657, 2023). "AIDs risk in both Caucasians and Asians was associated with the IFIH1 rs3747517 polymorphism." (PMID 37426657, 2023). "Previous meta-analyses have mostly focused on one or two AIDs or just one polymorphism, whereas the present study aimed to comprehensively examine the possible association between three common IFIH1 polymorphisms (rs1990760, rs3747517, and rs10930046) and the risk of seven common AIDs." (PMID 37426657, 2023). "As a gene closely related to the pathogenesis of AIDs, IFIH1 has attracted much attention." (PMID 37426657, 2023). "Therefore, to overcome the limitations of individual studies, and resolve inconsistencies, we conducted an all-sided meta-analysis of the association between three SNPs, including rs1990760, rs10930046, and rs3747517, in the IFIH1 gene and multiple AIDs including SLE, T1D, GD, HT, RA, AAD, and MS." (PMID 37426657, 2023). "Thus, IFIH1 may induce the occurrence of AIDs through the JAK-STAT signaling pathway." (PMID 37426657, 2023).
candidiasis (3 papers, 2015 to 2025). Infection with the organism Candida. "In contrast, downregulation of IFIH1 expression is associated with increased susceptibility to candidiasis, as observed in patients carrying IFIH1 gene polymorphisms compared to healthy individuals." (PMID 41249509, 2025). "Missense variants in IFIH1 encoding the IFI-I-inducing receptor MDA5 increased susceptibility to candidiasis." (PMID 36006878, 2022). "The MDA5/MAVS receptor system mediates IFN-I and type III IFN (IFN-III) responses and resistance to aspergillosis, and the same polymorphisms in IFIH1 that mediate susceptibility to candidiasis also predispose for aspergillosis." (PMID 36006878, 2022).
chronic periodontitis (3 papers, 2020 to 2025). A chronic inflammatory process that affects the tissues that surround and support the teeth. "Two common variants (rs1990760 and rs3747517) in IFIH1 were genotyped in PsO patients, chronic periodontitis patients, and the shared controls." (PMID 34899832, 2021).
hepatitis C (3 papers, 2021 to 2024). "The current study genotyped three SNPs (IFIH1 rs10930046 and DHX58 rs2074158, rs2074160) to assess their association with the chronicity of hepatitis C virus (HCV) infection among 1,590 participants (590 spontaneous HCV clearance cases and 1,000 persistent infection patients)." (PMID 36743960, 2023).
pulmonary hypertension (3 papers, 2020 to 2025). Increased pressure within the pulmonary circulation due to lung or heart disorder. "In view of our case and the previous association with pulmonary hypertension, we advocate detailed cardiopulmonary evaluation and monitoring for patients with AGS, especially those with IFIH1 mutations." (PMID 32508843, 2020). "Interestingly, a recent study revealed the presence of pulmonary hypertension in some patients with AGS, particularly in those with IFIH1 mutations." (PMID 32508843, 2020).
respiratory infections (3 papers, 2020 to 2022). "We detail the clinical case of an infant who initially presented with Pneumocystis jirovecii pneumonia (PCP), had recurrent respiratory infections, and was later treated with a JAK inhibitor, baricitinib, because of a genetically confirmed GOF mutation in the IFIH1 gene." (PMID 36685504, 2022). "PCP and recurrent respiratory infections have not previously been described as part of the clinical spectrum associated with a GOF mutation in the IFIH1 gene." (PMID 36685504, 2022).
Spastic paraplegia (3 papers, 2016 to 2025). Complete loss of the ability to move the lower limbs accompanied by spasticity of the lower limbs. "Exome sequencing indicated a missense IFIH1 mutation (c.1483G > A; p.Gly495Arg), which was reflected as spastic paraplegia that was correlated to the level of Type I interferon." (PMID 31427910, 2019). "Interestingly, another mutation associated with spastic paraplegia is the IFIH1 gene that encodes MDA5, strongly supporting the role of dsRNAs in such diseases." (PMID 27999332, 2016).
tuberculosis (3 papers, 2022 to 2025). A chronic, recurrent infection caused by the bacterium Mycobacterium tuberculosis. "Many interferon pathway-related genes, including STAT1,GBP1,GBP5, IFI44, IFIH1, FITM3, have been described in whole-blood transcriptome studies of tuberculosis." (PMID 36059536, 2022).
anemia (2 papers, 2017 to 2026). A reduction in the number of red blood cells, the amount of hemoglobin, and/or the volume of packed red blood cells. "Consistent with the Ifih1-/--dependent anemia, there were reduced numbers of mature CD71-Ter119+ erythroid cells in the BM of animals with this genotype." (PMID 28874170, 2017). "All Ifih1-/- animals, irrespective of Adar1 status, presented with a mild anemia compared to the C57BL/6 cohorts." (PMID 28874170, 2017).
Cerebral atrophy (2 papers, 2021 to 2024). Atrophy (wasting, decrease in size of cells or tissue) affecting the cerebrum. "Aicardi-Goutières (AGS) is a rare immune dysregulated disease due to mutations in TREX1, RNASEH2A, RNASEH2B, RNASEH2C, SAMHD1, ADAR1 or IFIH1, characterized by encephalopathy, dystonia, basal ganglia calcifications, white matter abnormalities, and cerebral atrophy." (PMID 33482855, 2021).
Hyperglycemia (2 papers, 2020 to 2025). An increased concentration of glucose in the blood. "Several interferon-stimulated genes (Bst1, Ifit1bl2, Ifih1) were also upregulated, indicating that B12 restored interferon responsiveness, which is often impaired under hyperglycemia." (PMID 41463345, 2025).
Immunodeficiency (2 papers, 2017 to 2026). Failure of the immune system to protect the body adequately from infection, due to the absence or insufficiency of some component process or substance. "Several rare biallelic IFIH1 mutations lead to profound immunodeficiency, while heterozygous mutations associate with milder clinical presentations." (PMID 41695592, 2026). "This would be needed to determine the causative agent in future episodes of acute and severe infection and to further substantiate our hypothesis of monogenic immunodeficiency due to IFIH1 deficiency." (PMID 29018476, 2017).
leukopenia (2 papers, 2022 to 2026). "The combination model of MX2 and IFIH1 could determine high-risk patients with leukopenia, and the combination model of IFIT3 and IFIH1 had a definite diagnostic accuracy in detecting fever among patients with SLE." (PMID 35757684, 2022). "The combination model of MX2 and IFIH1 was also good at determining the leukopenia group in patients with SLE, and the regression model was 5.6248 + −2.5919 × MX2 + 2.0122 × IFIH1 (AUC = 0.811)." (PMID 35757684, 2022).
pericarditis (2 papers, 2023 to 2024). An inflammatory process affecting the pericardium. "Eleven variants were located in genes already associated with recurrent pericarditis (NLRP3, TNFRSF1A and MEFV) and five in inflammation/immunodeficiency-related genes (IFIH1, NFKBIA, JAK1, NOD2 and ALPK1)." (PMID 39347728, 2024).
, and mouth disease (1 paper, 2022). "This research aimed to explore the association between the RIG-I-like receptor (RIG-I and MDA5 encoded by DDX58 and IFIH1, respectively) pathways and the risk or severity of hand, foot, and mouth disease caused by enterovirus 71 (EV71-HFMD)." (PMID 35041675, 2022).
Addison' s disease (1 paper, 2009). "On the basis on this finding we investigated the role of IFIH1 rs1990760 polymorphism in ATD including GD, HT and Addison's disease (all Germans) and enlarge our analysis in the transmission of this polymorphism in families with offspring affected with GD and HT." (PMID 19961590, 2009).
Aicardi–Goutières syndrome type 7 (1 paper, 2022). "Heterozygous gain-of-function mutations in the IFIH1 gene underlie a spectrum of autoinflammatory phenotypes including Aicardi–Goutières syndrome type 7 (AGS7) and Singleton-Merten syndrome type 1 (SGMRT1)." (PMID 35410415, 2022).
Anosmia (1 paper, 2022). An inability to perceive odors.
Anxiety (1 paper, 2021). Intense feelings of nervousness, tension, or panic often arise in response to interpersonal stresses. "Meanwhile, we also noted the underexpression of Ifih1 in both the two susceptible groups, which probably was an important pathological clue for depression and anxiety." (PMID 34603401, 2021).
Cognitive impairment (1 paper, 2024). Abnormal cognition is characterized by deficits in thinking, reasoning, or remembering. "The study examined the interaction between five hub genes (Cxcl10, Gbp2, Cxcl12, Cxcr3, Ifih1) and four distinct immune cell types (M1 macrophages, NK resting cells, memory CD4 T cells, naive CD8 T cells) in mice brain tissues affected by cognitive impairment." (PMID 39286150, 2024).
colorectal tumors (1 paper, 2023). "Furthermore, PHF8 mRNA levels negatively correlated with IFNG, TLR3, IFIH1, STAT1 and OASL expression, suggesting that PHF8 restrains adaptive immune responses in human colorectal tumors." (PMID 37454216, 2023).
combined immunodeficiency (1 paper, 2022). A broad classification of inherited disorders presenting at birth that affect both the cell-mediated and humoral aspects of the immune response. "We have detailed the case of an infant with early-diagnosed AGS type 7 with genetically confirmed heterozygous GOF mutation in the IFIH1 gene who initially presented neurological manifestations as well as P. jirovecii pneumonia (PCP) resembling combined immunodeficiency (CID)." (PMID 36685504, 2022).
coronary artery disease (1 paper, 2018). "In addition, an exploratory analysis demonstrated a nominally lower risk of coronary artery disease among IFIH1 pLOF carriers." (PMID 29691411, 2018).
disseminated candidiasis (1 paper, 2025). Systemic candidiasis occurs when Candida yeast enters the bloodstream and may spread (becoming disseminated candidiasis) to other organs, including the central nervous system, kidneys, liver, bones, muscles, joints, spleen, or eyes. "Infection of MDA5-deficient splenocytes or PBMCs with IFIH1 mutations showed altered pro- and anti-inflammatory cytokine profiles compared to WT controls, potentially contributing to increased susceptibility to disseminated candidiasis." (PMID 41249509, 2025).
gestational diabetes (1 paper, 2024). Carbohydrate intolerance first diagnosed during pregnancy. "It indicated a connection between variants of the IFIH1 gene and its protective effect on the likelihood of developing gestational diabetes mellitus (GDM)." (PMID 38926794, 2024).
H1N1 virus infection (1 paper, 2018). "Our RNA-Seq data identifies marked up-regulation of RLR family members, RIG-I, IFIH1, and DHX58 in response to H5N1 virus infection compared with H1N1 virus infection." (PMID 29475453, 2018).
hereditary spastic paraplegia (1 paper, 2019). Hereditary spastic paraplegias (HSP) comprise a genetically and clinically heterogeneous group of neurodegenerative disorders characterized by progressive spasticity and hyperreflexia of the lower limbs. "Here, the pathogenesis of an IFIH1 gene mutation is discussed through the analysis of a sporadic case of hereditary spastic paraplegia." (PMID 31427910, 2019). "Hereditary spastic paraplegia related to IFIH1 gene mutations is very rarely observed in practice." (PMID 31427910, 2019). "However, based on our extensive literature review, only one case of hereditary spastic paraplegia related to mutations of IFIH1 has been reported." (PMID 31427910, 2019).
leukemia (1 paper, 2013). A malignant (clonal) hematologic disorder, involving hematopoietic stem cells and characterized by the presence of primitive or atypical myeloid or lymphoid cells in the bone marrow and the blood. "We over-expressed IFIH1 in a K562 leukemia cell line and measured cell death for each risk SNP, comparing with the ancestral protective allele." (PMID 23441136, 2013).
lichen planus (1 paper, 2023). A chronic, recurrent, pruritic inflammatory disorder of unknown etiology that affects the skin and mucus membranes. "For instance, an enhanced IFIH1 expression is detected in the skin of chronic discoid lupus and lichen planus patients." (PMID 38022551, 2023).
nasopharyngeal carcinoma (1 paper, 2022). A carcinoma arising from the nasopharyngeal epithelium. "(2020) reported top three hub genes of PPI network of FANCI, POSTN, IFIH1, ZMYND10, PACRG and POU2AF1 for nasopharyngeal carcinoma biomarkers using STRING database PPI network construction with MCODE for module analysis." (PMID 36299526, 2022).
pancreatic autoimmunity (1 paper, 2010). "Further functional studies will help elucidate the mechanisms by which normal or wild type function of IFIH1 predisposes to pancreatic autoimmunity." (PMID 20844740, 2010).
Pancytopenia (1 paper, 2021). An abnormal reduction in numbers of all blood cell types (red blood cells, white blood cells, and platelets). "The patient also experienced unexplained pancytopenia, suggesting that the hemic system may have been affected by a gain-of-function mutation in the IFIH1 gene." (PMID 34054923, 2021).
Progressive encephalopathy (1 paper, 2023). "Several studies have shown that genetic polymorphisms of IFIH1 are associated with autoimmune-related diseases and AGS (a rare progressive encephalopathy)." (PMID 36743960, 2023).
prostate carcinoma (1 paper, 2022). A carcinoma that arises from epithelial cells of the prostate gland. "Studies show down‐regulation of the IFIH1 gene is associated with Docetaxel resistance in prostate cancers." (PMID 35810383, 2022).
soft tissue sarcoma (1 paper, 2023). A malignant neoplasm arising from muscle tissue, adipose tissue, blood vessels, fibrous tissue, or other supportive tissues excluding the bones. "In soft tissue sarcoma, a signature consisting of SECTM1 and other four immune-related genes, IFIH1, CTSG, STC2, and BIRC5, could predict prognosis and the responses to ICIs23 These evidence further enhanced the correlation of SECTM1 with anti-tumor immunity." (PMID 36818292, 2023).
steatosis (1 paper, 2021). Increased lipid within the cytoplasm of cells. "When compared to the gene correlation matrix in the steatosis and control samples within the training data, the IFIH1 gene is positively correlated to BTK in the steatosis samples." (PMID 34829865, 2021).
infection (491 papers, 2006 to 2026). The state of being infected such as from the introduction of a foreign agent such as serum, vaccine, antigenic substance or organism. "In view of this highly analogous constellation, it is unlikely that sole homozygosity for the IFIH1 nonsense mutation would have led to congenital symptoms (unrelated to infections) in patient II:1." (PMID 29018476, 2017). "Searching the WES data for additional homozygous variants identified a rare homozygous nonsense mutation, p.Lys889∗, in IFIH1, a likely cause for the enhanced susceptibility to infections." (PMID 29018476, 2017). "Indeed, patients carrying IFIH1 mutations show altered pro- and anti-inflammatory cytokine profiles, correlating with increased infection risk." (PMID 41249509, 2025). "We put forward the hypothesis that strong antiviral defense was harmful and loss of ZBP1 and IFIH1 provided an evolutionary advantage by increasing tolerance to infections by certain RNA viruses, including coronaviruses." (PMID 32574256, 2020). "Upon activation during infection, IFIH1 can also promote STAT1 transcription, facilitating M1 polarization in macrophages and intensifying inflammation." (PMID 40625749, 2025). "The RNA-sensor Mda5 (IFIH1) is an essential mediator of type I IFN production following infection with Rhinovirus or respiratory syncytial virus (RSV)." (PMID 40552831, 2025). "In agreement with this, our transcriptomic analysis identified an increase in expression in the viral sensors Ddx58 (RIG-I) and Ifih1 (MDA-5) following infection." (PMID 40065806, 2025). "Neutrophils, which were identified in the brain at only small relative abundance, dramatically expanded in the blood after infection and upregulated antiviral response genes, including Ddx58, Ifih1, Ifit1, Ifit2 and Isg15." (PMID 39749347, 2024). "We observed that IFIH1 expression was more than twofold greater following infection with HRV-16 as compared to following SARS-CoV-2 infection (p = 0.003)." (PMID 35484173, 2022). "Upon Tha and Th2P-4M infection, foetal pAstrocytes strongly induced the expression of IFIH1, CCL5, and CXCL10, whereas hiMicros strongly upregulated expression of CXCL10 and genes coding for antiviral proteins ISG15 and MX1." (PMID 36680128, 2022). "Despite increased Ifih1 gene expression on day 3 post infection, diminished RIG-I like receptor signaling was observed in aged H3N2 infected lung on day 5 and 7 post infection." (PMID 34829979, 2021). "FTSJ3 is involved in the processing of 34S pre-rRNA to 18S rRNA and in 40S ribosomal subunit formation and is used by HIV-1 to evade innate immune recognition by IFIH1/MDA5 in cases of infection by HIV-1 virus." (PMID 33752626, 2021). "As for SCs, Ifih1-ShRNAs infection increased the number of melanin-producing cells in Adar1 mutants (49 ± 12, **p < 0.01), suggesting that concomitant deletion of Mda5 at least partially rescue pigmentation defects." (PMID 31924792, 2020). "RIG-I was transcribed with medium expression and upregulated at 60 h after infection, while MDA5 (IFIH1) showed low mRNA levels." (PMID 33101221, 2020). "More importantly, upon CVB4 infection, these heterozygous mice were completely protected from diabetes onset while about 50% of homozygous NOD mice carrying a full complement of IFIH1 developed T1D within 7 days of infection." (PMID 29018409, 2017). "Several RNA virus associated PRRs, including DDX58, IFIH1, TLR7, and TLR8, were regulated according to infection status, being up-regulated at 24 h pi, and showing little or negligible change in expression during the rest of the study." (PMID 26893019, 2016). "No allelic bias was detected in resting PBMCs possibly due to the low levels of transcript available for amplification or that the effect of allelic variation on IFIH1 transcription only manifests in conditions of stimulation, stress or infection in vivo." (PMID 20844740, 2010).